APOE (apolipoprotein E)
Diseases named in the same sentence as APOE in open-access papers (continued):
Sharing a sentence is not in itself a finding about the gene and the disease.
memory impairment (continued). "APOE ε4-negative patients are characterized by relatively more nonamnestic deficits and anatomically by greater frontoparietal atrophy, while APOE ε4-positive patients predominantly demonstrate memory impairment and temporal lobe atrophy." (PMID 30086796, 2018). "Moreover, ApoA1/ApoE KO mice showed increased plasma amyloid 1-42 levels and exacerbated memory impairment, suggesting an important role of more than one apolipoprotein in the clearance of amyloid 1-42 from the brain." (PMID 41516203, 2025). "In summary, APOE mimic peptide TREM2 is a promising drug targetto relieve memory injury resulting from sleep deprivation, but moreevidence still needs to be collected to demonstrate the effect ofthe APOE mimic peptide on memory impairment induced by sleep lossin human beings." (PMID 40629727, 2025). "APOE ε4+ AD patients tend to exhibit more pronounced memory impairment." (PMID 38891891, 2024). "Memory impairment in aged ApoE-/- mice was found significantly ameliorated by Atorvastatin." (PMID 38048213, 2023). "Participants with more memory impairment were included in our investigation, which may have resulted in a higher carrier rate of APOE ε4." (PMID 35720695, 2022). "Furthermore, the APOE-4 allele influenced the severity of MTA and memory impairment in the aMCI subjects." (PMID 35492717, 2022). "Together, these data point to an apparent age-related inflammation in the hippocampus and may explain the more pronounced hippocampal-dependent memory impairment in aged ApoE-/- mice." (PMID 34349106, 2021). "Most notably, however, NeuN immune staining only significantly differed in hippocampus but not cortex where neither age nor treatment affected NeuN expression, further supporting a prominent hippocampus-dependent memory impairment in aged chronically hypercholesterolemic ApoE-/- mice." (PMID 34349106, 2021). "We sought to investigate the distribution of APOE genotypes across the full clinical AD spectrum including AD, late-stage amnestic mild cognitive impairment (L-aMCI), early-stage aMCI (E-aMCI), subjective memory impairment (SMI), and controls." (PMID 32770103, 2020). "Meanwhile, APOE-ε4 carriage showed a leading effect on memory impairment (P < 0.05)." (PMID 31831047, 2019). "We also observed that APOE-ε4 carriage showed a leading pathological effect on memory impairment." (PMID 31831047, 2019). "The APOE ε4 allele is believed to play an important role in insulin’s effects as AD patients without the APOE ε4 allele showed beneficial effects following memory impairment, whilst those with it had none." (PMID 26556341, 2015). "This decrease indicates that APOE ε4 may contribute to the declines of brain glucose metabolism in parahippocampal gyrus, which might lead to the memory impairment." (PMID 26161964, 2015). "As the NMDAR component of synaptic transmission has been shown to decline during aging, NMDAR activation may provide a mechanistic pathway for understanding apoE-related memory impairment." (PMID 25871877, 2015). "To date, the literature suggests that physical inactivity may exacerbate the effects of the APOE-ε4 genotype on AD-related neuropathology and its clinical manifestation of memory impairment, consistent with the current findings." (PMID 24795624, 2014). "Knockout of the TRPV1 gene in a mouse model in which the murine ApoE gene locus was replaced by the human APOE3 or APOE4 gene exacerbated Tau pathology and recognition and memory impairments." (PMID 38202764, 2023). "Likewise, the predominant FCM did not vary significantly across APOE genotypes (p = 0.7248), with memory impairment being the most frequent presentation in all groups." (PMID 40869250, 2025). "In addition, apoE4 mice a exhibit greater memory impairment than apoE-knockout (apoE-KO) mice, suggesting that apoE4 confers a gain of negative function." (PMID 17062143, 2006).
aneurysm (79 papers, 2009 to 2025). Bulging or ballooning in an area of an artery secondary to arterial wall weakening. "In the present study, treatment with gasdermin inhibitor disulfiram reduced aneurysmal aortic diameter enlargement, lowered AAA incidence, and ameliorated aneurysm severity in ApoE deficient mice following Ang II infusion." (PMID 37371479, 2023). "In order to evaluate the potential of a multi-target MRI approach to evaluate the risk of aneurysm rupture, a longitudinal study of ApoE−/− knockouts was performed, herein after referred to as study 1 (n = 13)." (PMID 32939002, 2020). "In susceptible mice, such as those which are apolipoprotein E deficient (ApoE-/-), AngII induces aortic dissection and aneurysm development in the supra-renal and thoracic aorta." (PMID 33008131, 2020). "In order to confirm the phenotypic differences in the two aneurysm models resulting from Opg deficiency, we crossed Opg KO mice with ApoE KO mice to generate ApoE-/-Opg-/- mice." (PMID 32614927, 2020). "Although the molecular mechanisms of the association between ApoE and aneurysms are not fully understood, they are becoming increasingly clear." (PMID 29769126, 2018). "This study is the first report describing whole genome expression arrays in the apolipoprotein E deficient mice in relation to aneurysm formation." (PMID 19580648, 2009). "The aim of the current study was to identify genes and pathways associated with aneurysm formation in the angiotensin II infused ApoE-/- mouse model." (PMID 19580648, 2009). "Additionally, aneurysms in AngII-infused ApoE–/– mice have also been associated with the increased expression of TGF-β in whole-genome expression analysis, suggesting a possible synergic effect between TGF-β and AngII signaling." (PMID 36472907, 2023). "To determine whether there is a common underlying mechanism to explain the impact of Opg deficiency on the vascular structure of the two aneurysm models, we analyzed suprarenal aortic tissue of 6-month-old ApoE-/-Opg-/- mice after AngII infusion for 28 days." (PMID 32614927, 2020). "The spontaneous development of aneurysms in ApoE KO mice is rare, however, ecCNP/ApoE double-KO mice are more susceptible to this phenomenon, suggesting that CNP may help to maintain the structural integrity of the vessel wall." (PMID 31072047, 2019). "Firstly we aimed to identify genes which might underlie the protection of the infrarenal aorta from aneurysm formation in ApoE-/- mice." (PMID 19580648, 2009). "First, Although Ang II-induced ApoE-/- mice mainly develop dissecting aneurysms, this model provides key insights into acute inflammation and vascular remodeling." (PMID 40140755, 2025). "To investigate the expression of Nox1 in aneurysm tissues, we isolated abdominal aortas from ApoE−/− mice that were subcutaneously infused with Ang II for 28 days." (PMID 39721498, 2025). "Four weeks after AngII infusion, the ATF4-knockdown (AngII+sh-ATF4) mice showed significantly smaller aneurysm formation compared with ApoE-/- (AngII) mice, while ATF4-overexpression (AngII+oe-ATF4) mice showed aggravated AAA formation." (PMID 38913045, 2024). "Even though aneurysm formation only develops in the ApoE model with AngII infusion also ECs from our sham mice (ApoE−/− with western diet) showed an altered pro-inflammatory gene expression pattern compared to WT animals." (PMID 38965173, 2024). "Gene expression of ECs from aneurysms of the AngII ApoE−/− model when compared to sham animals mimicked expression patterns from predilection sites of healthy animals." (PMID 38965173, 2024). "Use of this probe enabled differentiation between collagen-rich and collagen-poor aneurysms, of which the latter is more prone to rupture, in AngII-infused ApoE−/− mice." (PMID 35492343, 2022).
aneurysm (continued). "Previous studies have already noted the discrepancy between CD206 and APOE expression, but both are considered resident macrophage markers in tumors and aneurysms alike." (PMID 35874788, 2022). "Autologous bone marrow MSCs are effective for regression of aneurysms in Ang II-induced ApoE−/− mice." (PMID 34489714, 2021). "ET-1 overexpression induces aneurysms in apolipoprotein E knockout mice with increased oxidative stress levels and monocyte/macrophage infiltration." (PMID 33672844, 2021). "Knockout of VSMC MT1-MMP in apoE−/− (Mmp14−/−/apoE−/−) mice increased the size of atherosclerotic plaques and promoted the formation of aneurysm likely through promoting proinflammatory responses and enhancing smooth muscle proliferation." (PMID 34297054, 2021). "We investigated the role of CCN4 in a mouse aneurysm model, using apolipoprotein-E knockout (ApoE−/−) mice fed high fat diet and infused with Angiotensin II (AngII)." (PMID 34080128, 2021). "Everolimus, a rapamycin blocker, inhibited Ang II-induced aneurysm in ApoE−/− mice through diminished M1 polarization and suppressed the development of bone marrow CCR2 monocytes." (PMID 34489714, 2021). "On the other hand, miR-181b inhibition by locked nucleic acid resulted in decreased aneurysm formation and stabilized aneurysms in ApoE−/− mice infused with angiotensin II." (PMID 34071976, 2021). "This study illustrates that deletion of CCN4 leads to a retardation of aneurysm progression in the thoracic and abdominal aortae of ApoE−/− knockout mice." (PMID 34080128, 2021). "Up to date, the universal model of aneurysm formation has been the infusion of AngII to ApoE KO mice." (PMID 32617140, 2020). "By contrast, in AngII-infused ApoE−/− mice, large immunopositive fluorescent areas were observed in the aneurysm wall with higher intensity and larger fluorescent areas." (PMID 32094414, 2020). "Concurrently, collagen accumulation in the adventitia induced by AngII infusion in ApoE-/-/Opg-/- mice limits the development of aneurysms and dissection." (PMID 32614927, 2020). "To understand how Opg deficiency contributes to adventitial thickening, we examined the expression of Trail in aneurysm tissue of AngII-infused ApoE-KO mice, given the known role of Opg as a decoy receptor for Trail." (PMID 32614927, 2020). "In further studies, AAA models were generated in ApoE−/− mice by chronic infusion of Ang II for 28 or 42 days, showing a typical aneurysmal phenotype or aneurysm rupture." (PMID 32817651, 2020). "The authors of that study attributed the lower incidence of aneurysms and rupture in ApoE-/-Opg-/- mice to the down-regulation of proteolytic enzyme expression." (PMID 32614927, 2020). "The classical model of AAA induction is based on AngII infusion in ApoE knockout (ApoE KO) mice, which lead to 70-80% aneurysm incidence." (PMID 32617140, 2020). "It has been reported that high levels of IL-10 are detected in the serum of patients with aneurysms and that IL-10−/− counteracts Ang II-induced vascular dysfunction in APOE−/− mice." (PMID 32509885, 2020). "In the AngII-induced ApoE KO mouse aneurysm model, local medial destruction is observed only in the plaque area." (PMID 32614927, 2020). "We found that osteoclastogenesis plays an important role in the development of aneurysms through stimulation of TRAP-positive macrophages (TPMs) in the CaPO4 and angiotensin II (AngII)-infused apolipoprotein E-deficient (apoE−/−) mouse models." (PMID 31546645, 2019). "To examine the effect of CJ‐42794 on aneurysm formation, we use ApoE−/− mice infused with angiotensin II for 4 weeks." (PMID 30230255, 2018). "Increased apoptosis (detected by TUNEL, caspase-3 activity and histone-associated DNA fragmentation) was observed in angiotensin-II (Ang-II) induced aneurysms in the apolipoprotein E null (Apoe−/−) mouse model." (PMID 29229950, 2017).
aneurysm (continued). "Future studies of aneurysm mechanics using the ApoE-/-/angiotensin-II model would be better in assuming pulse pressure profiles consistent with our telemetry findings instead of attempting to measure pulse pressure in individual mice." (PMID 26086817, 2015). "The AngII-induced aneurysm formation in ApoE−/− mice mirrors many characteristics of the human AAA, such as increase of inflammatory response, enhancement of MMP activity, depredation of extracellular matrix, and rupture of aortic elastic layer." (PMID 25431606, 2014). "In a murine model of AAA, apolipoprotein E-knockout mice infused with 1,000 ng/kg/min angiotensin II, treatment with clopidogrel, an inhibitor of platelets, significantly suppressed aneurysm formation (47% decrease, P<0.05)." (PMID 23284748, 2012). "In a subsequent study, we demonstrate that adventitial decorin is reduced in apoE-KO aneurysms at sites adjacent to thrombi and in areas of injury." (PMID 22479366, 2012). "Our findings demonstrate that aneurysms forming in ApoE-/- mice have marked influx by a range of inflammatory cells and upregulation of cytokines which have all been previously demonstrated in human AAA." (PMID 19580648, 2009). "These and other disparities between this mouse model and human AAA stimulated us to investigate the gene expression profile of aneurysms in the ApoE-/- mouse model." (PMID 19580648, 2009). "When we compared the gene expression pattern of ECs from aneurysms of the abdominal segment of AngII ApoE−/− mice with shams we found very similar categories to be regulated with ECM organization, cell adhesion, positive regulation of EC migration and immune receptor activity." (PMID 38965173, 2024). "Interestingly, this expression pattern reflected genetic and structural changes at the sites of AA development in the AngII ApoE−/− aneurysm model." (PMID 38965173, 2024). "In the vast majority of the AngII ApoE−/− mice we found aneurysms in the respective locations (7/9 asc, 8/9 abd) that could also be detected by ultrasound imaging." (PMID 38965173, 2024). "Finally, the role of MCs in aneurysmal progression was further analysed in vivo in ApoE-/- mice subjected to angiotensin II infusion aneurysm model, through MC-specific depletion after the establishment of dissecting aneurysms." (PMID 38055674, 2023). "To test this hypothesis, we performed RNA-Seq analysis of the abdominal aorta and thoracic aorta in an Ang II-induced aneurysm model in comparison to their saline-treated ApoE-KO counterparts." (PMID 37731512, 2023). "Using RNA sequencing data from AngII-infused ApoE−/− aneurysm tissue, we identified 386 differentially expressed genes (DEGs) in FAM3A overexpression tissues compared to those of Ad-sham control tissues (|log2FC| > 1 and FDR < 0.05): 192 upregulated and 194 downregulated transcripts." (PMID 37660071, 2023). "Furthermore, the putative pathogenic role of MCs in aneurysmal growth was evaluated in vivo, by inducing MC depletion in Red Mast cell and Basophil (RMB)—ApoE-/- mice subjected to angiotensin II infusion during the phase of aneurysm progression." (PMID 38055674, 2023). "The lipid-lowering effects of naringenin may partially account for its anti-aneurysm effect on ApoE−/− mice." (PMID 35228523, 2022). "Moreover, ApoE KO mice showed a greater formation of atherosclerotic plaque and aneurysms than ApoE KO mice crossed with CNP ecKO mice." (PMID 36101368, 2022). "This in turn could have resulted in smaller aneurysms and a lower rate of dissection events in ApoE-/-Opg-/- mice in the AngII-induced aneurysm model." (PMID 32614927, 2020). "A preventive role for osteoprotegerin (Opg) in the development of abdominal aortic aneurysm has been reported in the CaCl2-induced aneurysm model, whereas Opg was found to promote suprarenal aortic aneurysm in the AngII-induced ApoE knockout mouse aneurysm model." (PMID 32614927, 2020).
aneurysm (continued). "However, another group reported that Opg can promote the development of aneurysms in the suprarenal aorta (SRA) in the AngII-induced ApoE KO mouse model." (PMID 32614927, 2020). "However, we observed adventitial thickening accompanied by myofibroblast accumulation and increased expression of collagen I and Trail in aneurysm tissue of ApoE-/-Opg-/- mice." (PMID 32614927, 2020). "To evaluate the potential of delayed-enhancement MRI using gadofosveset as a prognostic tool for aneurysm rupture, we performed a longitudinal study of ApoE−/− mice with gadofosveset imaging after 1 week of AngII infusion and with fatal aneurysm rupture as the endpoint (study 1, n = 18)." (PMID 32094414, 2020). "There was an increase in the CNR of the aneurysm region with progression of AAAs in ApoE−/− mice." (PMID 32094414, 2020). "This facet of CNP biology is clearly important in the context of atherosclerosis as genetic ablation of CNP leads to an increase in the development of atherosclerotic lesions, greater infiltration of macrophages, and the formation of aortic and abdominal aneurysms in ecCNP/ApoE double-KO mice." (PMID 31072047, 2019). "ApoE−/− mice with large blood-filled aneurysms at the time of harvest were excluded from the analysis because of the confounding effect of blood cells trapped in aneurysms to the flow cytometric analysis of aortic cells." (PMID 30048944, 2018). "In conclusion, administration of 0.8 mg/kg/day Ang II into ApoE−/− mice following BMT caused a reduction in aneurysm formation and rupture compared to non-BMT mice administered with the same dose, although systolic blood pressure remain unchanged." (PMID 30048944, 2018). "From the study of 122 good-grade aSAH patients, our major finding is that those aSAH patients carrying the APOE ε4 allele are predisposed to elevate ICP within 72 h of the ictus, after controlling for age, the severity of the hemorrhage, the aneurysm location, and other factors." (PMID 28469595, 2017). "When the aneurysms were classified according to location, size and WFNS grade and compared with different APOE genotype models and allele frequencies, only the PCOM aneurysm was statistically significant with ε2 vs. ε3 allele frequency (OR = 3.59, 95% CI = 1.11–11.64, p = 0.03)." (PMID 29213291, 2017). "In this paper, we present the results of longitudinal ultrasound studies using the elastase and AngII apoE−/− animal models to compare the changes in four important anatomic and biomechanical parameters: aneurysm diameter, aneurysm volume, circumferential cyclic strain, and blood flow velocity." (PMID 26064906, 2015). "Thus, in addition to reducing AAA incidence and mortality, telmisartan and irbesartan effectively suppress early aneurysm progression in the Ang II/ApoE−/− model." (PMID 23226500, 2012). "Since vascular smooth muscle apoptosis and inflammation have been demonstrated to be important mechanisms in human AAA, upregulation of Dapk1 and Cd59 may be relevant to the predilection of the suprarenal aorta to aneurysm formation in ApoE-/- mice." (PMID 19580648, 2009). "Indeed, diabetic ApoE−/− x eNOX5ki/ki mice formed more frequently aneurysms than ApoE−/− WT mice." (PMID 35798762, 2022). "This may be a possible mechanism of ApoE involved in the aneurysms and aSAH." (PMID 29769126, 2018). "An alternative ARB, losartan, inhibited AAA formation in the Ang II/ApoE−/− model as evaluated by size and structural determination at sacrifice, and both ARBs telmisartan and valsartan limited PPE-induced aneurysm progression in rats." (PMID 23226500, 2012). "Next, we analyzed aneurysms in the ascending arch and abdominal aorta derived from the AngII ApoE−/− model at d14 or d28 and compared them with the same sites in sham animals (ApoE−/− mice without AngII application)." (PMID 38965173, 2024).